CD34 (CD34 molecule)
Diseases named in the same sentence as CD34 in open-access papers (continued):
Sharing a sentence is not in itself a finding about the gene and the disease.
atherosclerosis (continued). "Pulse wave velocity and carotid intima-media thickness (cIMT), both patterns of preclinical atherosclerosis, were also evaluated in relation to inflammatory markers, CD34+ cell number, and vitamin D levels." (PMID 26241902, 2015). "Further insight into the role of progenitor cells in atherosclerosis in humans has focused on the use of cells that label both with CD34+, a marker of hematopoetic stem cells, and with KDR+, a marker of endothelial cell fate." (PMID 20407620, 2009). "Since aggressive endothelial repair induces a shortage of CD34-positive cells due to consumption, participants with established atherosclerosis (CIMT ≥ 1.1 mm) could have lower levels of circulating CD34-positive cells." (PMID 38565613, 2024). "Therefore, sufficient numbers of CD34-positive cells are mandatory for the development of structural atherosclerosis, as evaluated based on CIMT increase (Figure 1➂)." (PMID 37511963, 2023). "Therefore, individuals with sufficient numbers of circulating CD34-positive cells have aggressive endothelial repair that leads to both structural atherosclerosis and functional atherosclerosis (Figure 1➂)." (PMID 37511963, 2023). "The development of structural atherosclerosis requires circulating CD34-positive cells." (PMID 37099591, 2023). "Active arterial wall thickening (CIMT ≥ 0.01 mm/year), which indicates the status of yearly progression of CIMT, is inversely associated with baseline atherosclerosis (CIMT ≥ 1.1 mm), possibly due to the consumption of hematopoietic stem cells (CD34-positive cells)." (PMID 35159980, 2022). "Deficient endothelial repair related to a shortage of CD34-positive cells due to consumption furthers functional atherosclerosis but not structural atherosclerosis." (PMID 36528703, 2022). "The present study indicates that circulating CD34-positive cells might coordinate the beneficial influence of hypertension and structural atherosclerosis on health." (PMID 36528703, 2022). "Our previous prospective study of 363 Japanese males aged 60–69 years followed for two years revealed an inverse association between baseline atherosclerosis (CIMT ≥ 1.1 mm) and active arterial wall thickening (CIMT ≥ 0.01 mm/year), possibly due to lower levels of CD34-positive cells." (PMID 35159980, 2022). "Since circulating CD34-positive cells are required for active arterial wall thickening, participants with baseline atherosclerosis might have a lower chance of getting active arterial wall thickening." (PMID 36528703, 2022). "Hematopoietic stem cells, such as CD34-positive cells, might play an important role in the present results, as CD34-positive cells contribute to the development of structural atherosclerosis and progression of angiogenesis." (PMID 36290496, 2022). "Since circulating CD34-positive cells are necessary for active arterial wall thickening (CIMT ≥ 0.01 mm/year), participants with high circulating CD34-positive cells might have higher activity of progression of atherosclerosis and angiogenesis." (PMID 33549053, 2021). "Furthermore, subjects with baseline subclinical atherosclerosis should induce wasting reduction of circulating CD34+ cell which leads to a deficit of the source material for atherosclerosis development (active arterial wall thickening)." (PMID 32170211, 2020). "Therefore, a higher number of circulating CD34+ cells indicates that there is enough material for atherosclerosis to develop (active arterial wall thickening)." (PMID 32170211, 2020). "Furthermore, our previous studies revealed that a higher level of CD34-positive cell (at and above median values) is necessary for the development of atherosclerosis." (PMID 31785607, 2019). "The CD34-positive cell is a source of progression for atherosclerosis as those cells could differentiate not only into an endothelial cell but also into a foam cell." (PMID 31785607, 2019).
atherosclerosis (continued). "This paradoxical phenomenon between HGF and circulating CD34-positive cell count on atherosclerosis may result from a consumptive reduction of circulating CD34-positive cells." (PMID 29724162, 2018). "Since hypertension and endothelial dysfunction have a bidirectional relationship, circulating CD34-positive cell levels may influence the association between HGF and atherosclerosis." (PMID 29724162, 2018). "Additionally, platelets not only induce differentiation of human CD34-positive cells into endothelial cells, but also into foam cells, which are a contributing factor in the development of atherosclerosis." (PMID 27374094, 2016). "To investigate the correlation between platelets and circulating CD34-positive cells as a marker of vascular repair (endothelial repair and atherosclerosis development), we conducted a cross-sectional study of 567 men aged 60-69 who underwent an annual health check-up between 2013 and 2015." (PMID 27374094, 2016). "On the basis of these findings, it is tempting to speculate that the decreased frequency of CD34+ BM-CPCs by DM lead to a progression of atherosclerosis and increase the number of diseased coronary arteries in patients with IHD." (PMID 22118372, 2011). "Increased CD34+ cell count was associated with a decrease in extent of subclinical atherosclerosis in multiple arterial beds, independent of 10-year CVD risk." (PMID 20407620, 2009). "Therefore, LDLc could have a beneficial influence on preventing functional atherosclerosis that is related to CD34-positive cell shortages." (PMID 37511963, 2023). "Therefore, circulating CD34-positive cell count could influence the development of both structural and functional atherosclerosis." (PMID 36528703, 2022). "In particular, CD34+CPCs may contribute to vascular health by promoting endothelial turnover and angiogenesis; thus, CD34+CPCs could play an important role in endothelial repair that is crucial for contrasting atherosclerosis progression." (PMID 35885020, 2022). "Therefore, participants with baseline atherosclerosis might have fewer CD34-positive cells and less active arterial wall thickening." (PMID 35159980, 2022). "Our findings indicate that circulating CD34-positive cell levels could determine the influence of HGF on CIMT in elderly Japanese men and can be expected to serve as an effective tool for the clarification of the roles played by HGF and CD34-positive cells in the progression of atherosclerosis." (PMID 29724162, 2018). "Circulating progenitor cells (CD34+CPCs), including a cell subset defined as endothelial progenitor cells (EPCs),are recognised to contribute to postnatal vasculogenesis and to endothelial homeostasis,delaying the development of atherosclerosis and cardiovascular disease (CVD)." (PMID 28301500, 2017). "However, human endothelial progenitor cells (CD34-positive cells) are reported to differentiate into not only endothelial cells but also into foam cells, which are a contributing factor in the development of atherosclerosis." (PMID 26818627, 2016). "The existence of circulating CD34-positive cells in hypertensive men with high plasma platelet levels might no longer reduce the risk of atherosclerosis despite CD34-positive cells playing important role in endothelial repair." (PMID 27374094, 2016). "Yet another study found an association of a reduction in the number of endothelial progenitor cells (CD34-positive cells) with an increase in the number of infarctions >5 mm in diameter, but no such association with atherosclerosis in carotid arteries of patients with ischemic stroke." (PMID 26769093, 2016). "A shortage of CD34-positive cells leads to the development of functional atherosclerosis but not structural atherosclerosis." (PMID 37511963, 2023). "A shortage of CD34-positive cells, which results in insufficient endothelial repair, leads to the development of functional atherosclerosis but not structural atherosclerosis (Figure 1➅)." (PMID 37511963, 2023).
atherosclerosis (continued). "In the cross-sectional study based on 562 elderly men aged 60–69 years, among participants with high CD34-positive cells, γ-GTP showed significant and positive association with atherosclerosis, but not with hypertension." (PMID 33549053, 2021). "Among participants with high circulating CD34-positive cells (≥ median values), γ-GTP showed a positive association with atherosclerosis but not with hypertension." (PMID 33549053, 2021). "In this study, we showed that among elderly participants with high CD34-positive cell, the γ-GTP level shows a significant positive association with atherosclerosis but not with hypertension." (PMID 31785607, 2019). "The main findings of the present study are that among elderly participants with high CD34-positive cell, γ-GTP shows a significantly positive association with atherosclerosis but not with hypertension." (PMID 31785607, 2019). "In RA patients with moderate disease activity we found an interdependence between CD34+ cell number and early atherosclerosis, as defined by PWV increase and carotid intima-media thickening; CD34+ cell number, also, appears to be affected by low 25-OH D levels." (PMID 26241902, 2015). "The present study focusing on circulating CD34-positive cells, platelets, HTLV-1, and SNPs in VEGF, BRAP, and ALDH2 has shown that active endothelial repair, which leads to the progression of structural atherosclerosis, partly indicates the prevention of hypertension." (PMID 37511963, 2023). "Due to a shortage of CD34-positive cells, structural atherosclerosis does not develop, but the microcirculation might become disrupted, which elevates oxidative stress and might lead to residual hypertension." (PMID 36528703, 2022). "Unlike CD34-positive cells, which directly contribute to endothelial repair, reticulocytes also contribute to endothelial maintenance by reducing oxidative stress, which plays a crucial role in the pathogenesis of both atherosclerosis and hypertension." (PMID 33549053, 2021). "Bone marrow-derived hematopoietic stem cells (CD34-positive cells) contribute to endothelial repair not only by differentiation into endothelial cells but also into foam cells, which are known sources of atherosclerosis." (PMID 33549053, 2021).
neurofibroma (43 papers, 2010 to 2025). An intraneural or extraneural neoplasm arising from nerve tissues and neural sheaths. "The immunohistochemical findings–scarce S100 and focal CD34—strongly suggest a loss of the typical neurofibroma architecture (specifically, loss of the CD34-positive fibroblastic network), likely fulfilling a third criterion." (PMID 40700245, 2025). "Other markers such as the loss of CD34 lattice and the presence of mast cells were used to complement the histological analysis of the neurofibroma to MPNST sequence but warrant further study." (PMID 34445326, 2021). "In all the variants of neurofibroma, including localized, diffuse and plexiform types, double staining shows that the number of TCs/CD34+SCs can be higher than the number of Schwann cells." (PMID 32560571, 2020). "The neurofibromas in our porcine model selected for the study were immunoreactive for the two predominant neurofibroma diagnostic proteins, S100 and CD34; Masson’s Trichrome staining showed heavy collagen deposition with a large population of spindle-shaped cells and immune infiltrate." (PMID 37817770, 2023). "While immunohistochemical analysis has limited utility in diagnosing ANNUBP, a complete absence of S-100 protein/SOX-10 expression and the loss of the CD34+ fibroblast network, typically found in all neurofibroma variants, may serve as useful diagnostic indicators." (PMID 40308487, 2025). "In addition, both isolated and classical NF-associated neurofibromas may contain CD34+/fibroblastic multinucleated giant cells with the cytological features of the so-called “floret-like cells”, as commonly seen in spindle cell/pleomorphic lipoma." (PMID 35741273, 2022). "Although immunohistochemical analyses are not helpful for the diagnosis of ANNUBP, a variable to complete loss of S100 protein/SOX10 expression and a loss of the CD34-positive fibroblastic network, typically found in all types of neurofibromas, may be suggestive." (PMID 35741273, 2022). "Biopsy revealed a neurofibroma with hypercellularity, moderate atypia, scarce S100 positivity, focal CD34 positivity, and an elevated Ki-67 proliferation index of 10–12%, consistent with ANNUBP." (PMID 40700245, 2025). "Immunohistochemically, neurofibromas demonstrate variable but often diffuse S100 positivity in Schwann cells and CD34 expression in fibroblastic elements." (PMID 41234953, 2025). "We were also interested in CD34, which has been proposed to distinguish neurofibroma from desmoplastic melanoma by a fingerprint pattern of expression in the neurofibromas." (PMID 39804140, 2025). "An oral plexiform neurofibroma was confirmed with characteristic histopathological findings and strong positivity for S100, CD34, and toluidine blue staining." (PMID 39479119, 2024). "Later, CD34 was proposed as a neurofibroma fibroblast marker, although CD34+ cells are found in normal tissues." (PMID 34445326, 2021). "We have previously studied CD34+SCs/TCs in tumors originating from Schwann cells (neurofibroma and granular cell tumor)." (PMID 34298962, 2021). "The histopathology results showed wavy spindle cell changes, and immunohistochemical analysis mainly presented strong and diffuse CD34 positivity, which supported the neurofibroma changes." (PMID 33767727, 2021). "We confirm that the number of CD34+SCs/TCs can be higher than the number of Schwann cells in neurofibroma and that CD34+SCs/TCs surround granular cells in the granular cell tumor." (PMID 34298962, 2021). "These voluminous cells of increased somatic size show some retracted processes and resemble modified CD34+SCs/TCs in the plexiform type of neurofibroma, in which myxoid deposits can be prominent." (PMID 34298962, 2021). "An important population of TCs/CD34+SCs is present in neurofibromas, together with the remaining cellular components of the nerve (Schwann, perineurial and vascular cells) and mast cells." (PMID 32560571, 2020).
neurofibroma (continued). "In the plexiform type of neurofibroma, the myxoid deposits can be prominent, and TCs/CD34+SCs increase their somatic size, showing multiple intracytoplasmic vacuoles." (PMID 32560571, 2020). "For the CD34+ cells in neurofibromas and in Antoni B zones of neurilemoma, some authors use the term ‘ameboid dendritic CD34+ cells’." (PMID 32560571, 2020). "CD34 expression has also been demonstrated in the multinucleated floret-like cells sporadically seen in neurofibromas, which suggests a reactive change in the endoneurial cells." (PMID 32560571, 2020). "In neurofibromas, TCs/CD34+SCs and Schwann cells form bundles with a parallel, arciform or irregular arrangement, show a fusiform or stellate morphology and are associated with collagen fibres in a variable myxoid background." (PMID 32560571, 2020). "Immunohistochemical studies show neurofibromas to have CD34 positivity, variable S100 positivity, and rare EMA positivity if perineurial cells are present." (PMID 26709712, 2016). "The immunohistochemical analysis was accomplished and the positivity of spindle cells for CD-34 excluded the possibility of a traumatic fibroma while their negativity for S-100 excluded the possibility of a neurofibroma." (PMID 26491592, 2015). "Conversely, neurofibromas exhibit a high concentration of CD34-positive spindle cells." (PMID 39188505, 2024). "Early on, CD34+ S100-cells were identified in the microenvironment of neurofibroma." (PMID 34445326, 2021). "Although neurofibroma may show CD34 positivity, this entity is positive for S-100 protein and EMA, and the absence of cluster ectatic hyalinized vessel allows for a correct differential diagnosis." (PMID 33916538, 2021). "Instead, they may represent a subpopulation of non–Schwannian S100 protein- and CD34+ positive cells similar to CD34-positive endoneurial dendritic cells found in normal nerves and neurofibromas." (PMID 23890233, 2013). "Occasionally, multinucleated giant cells could also be seen in neurofibroma, which show CD34 and S-100 positive expression." (PMID 23148444, 2012). "Immunohistochemically, schwannomatous areas are strongly positive for S100 and SOX10, whereas the neurofibroma component expresses S100, SOX10, CD34, EMA, and GLUT-1." (PMID 40218204, 2025). "Histopathology confirmed a diffuse-type cellular neurofibroma with patchy S100 and SOX10 positivity, focal CD34 expression, and low Ki-67, supporting a benign profile." (PMID 41446319, 2025). "Immunohistochemistry revealed positivity for CD34 and S-100, but negativity for c-Kit, DOG-1, and smooth muscle actin, confirming neurofibroma." (PMID 40507589, 2025). "These neurofibromas exhibited classic diffuse-type histologic morphology and expected patterns of S100, SOX10, GFAP, and CD34 immunohistochemistry." (PMID 37817770, 2023). "Immunohistochemically, neurofibroma is typically an S100-protein- and SOX10-positive tumor with a variable expression of CD34 and EMA." (PMID 35741273, 2022). "The only case of neurofibroma/perineurioma also showed positivity for S100 in the neurofibromatous areas and for EMA and CD34 in the perineuromatous areas." (PMID 28526004, 2017). "On the other hand, these tumors lacked a whorly organization, verocay bodies, and CD34-positive fingerprints, which are often found in neurofibromas." (PMID 39804140, 2025). "Besides S-100 protein or Ki67 markers, antibodies like calretinin, CD34, factor XIIIa, and CD56 can also diagnose and confirm neurofibroma." (PMID 39149528, 2024). "As neurofibroma progresses to ANNUBP and MPNST, CD34 signal heterogeneity increases." (PMID 34445326, 2021). "Although differential diagnostic problems do exist between a diffuse neurofibroma infiltrating the dermis and DFSP, the co–expression of both CD34 and WT1 certainly does not help in their distinction." (PMID 33445443, 2021).